IRF3 (interferon regulatory factor 3)
Diseases named in the same sentence as IRF3 in open-access papers (continued):
Sharing a sentence is not in itself a finding about the gene and the disease.
viral infection (continued). "In this context, it is possible that reduced levels of IFN regulatory factor IRF3 or defective IRF7 function reduces the level of IFNα/β gene expression, increasing the sensitivity to viral infection." (PMID 36443794, 2022). "Interferon (IFN) regulatory factor 3 (IRF3), a key transcription factor, is involved in the synthesis of IFN and the IFN-stimulated genes (ISGs) during virus infection." (PMID 34619149, 2021). "Prior transfection of miR-24 inhibited IRF3 activation in HSV1 infected cells, whereas antimiR-24 enhanced it; consequently, IFN-β mRNA and IFIT-1 mRNA induction by virus infection was suppressed by miR-24 and augmented by antimiR-24." (PMID 34591940, 2021). "IRF3 is another transcription factor downstream of RIG-I signaling, which plays a vital role in innate immunity against viral infection." (PMID 34054851, 2021). "Viral infection activates the TLRs signaling pathway, then the MyD88, TRIF, Mal, and/or TRAM are recruited, subsequently activating IRF3 and IRF7 to promote the expression of IFN-β further." (PMID 35173691, 2021). "Both IRF3 and IRF7 serve as a critical role in IFN-I for combating viral infection if adequate IRF3 and IRF7 bind to the promoter sites of IFN-I genes." (PMID 34880855, 2021). "During viral infection, single-stranded RNA is recognised by RIG-I that induces downstream innate antiviral responses mediated by NF-κB and IRF3 resulting in IFN-β expression." (PMID 33931637, 2021). "Specifically, they suggested that following viral infection, TRIM26 enters the nucleus in order to bind IRF3 leading to its degradation." (PMID 33419081, 2021). "IFNs-induced protein 44-like (IFI44L) was identified as negatively modulator for innate immune response induced by virus infection, which interacts with FKBP5 to decrease the phosphorylation of IRF-3 and NF-B mediated by IKK and IKK, respectively." (PMID 34884921, 2021). "We also show for the first time that Bmp8a interacts with Alk6a, which promotes the phosphorylation of Tbk1 and Irf3 through p38 MAPK pathway, and induces the production of type I interferons (IFNs) in response to viral infection." (PMID 33750893, 2021). "Different from IRF3 that is constitutively expressed, IRF7 expression entirely depends on type I IFN signaling and is affected by viral infection." (PMID 33554733, 2021). "For RNA viruses, the major sensors RIG-I and MDA5 bind the adaptor molecule IPS1 upon virus infection, which activates TBK1 and IKKε, resulting in IRF-3 phosphorylation." (PMID 34335514, 2021). "In virus infection, short viral DNAs or RNAs bind with cGAS and, consequently, with phosphorylates STING in ER lumen for activating IRF3 and NFkB transcriptional factors." (PMID 34680466, 2021). "Upon virus infection, the upregulation of phosphorylated TBK1 was observed, whereas with the expression of CARDs, the phosphorylated IRF3 and further upregulation of phosphorylated TBK1 were obvious." (PMID 34177861, 2021). "ISG15 is a ubiquitin-like protein which is induced by viral infection, and IFN-α and -β, and can conjugate to target proteins such as IRF3." (PMID 34064193, 2021). "To assess changes in RIG-I and MDA5-mediated signaling cascades upon viral infection, we analyzed changes in the phosphorylation of TBK1 and IRF3, which are the downstream events of MAVS activation and hall marker of interferon pathway activation." (PMID 34016972, 2021). "Since IRF3 and IFN-β are the upstream players of FAM26F, and their expression is impaired during viral infection, hence FAM26F expression was also found to decrease upon HBV infection." (PMID 33639860, 2021). "The expressive proteins of IRF3 are equal in virus-infected XRN1 KO cells and A549 control cells, but p-IRF3 significantly increases in XRN1 KO cells after viral infection." (PMID 34311580, 2021). "Multiple transcription factors including NF-κB, IRF3, IRF7, and AP1 have been reported to promote IFN-I production upon virus infection." (PMID 34315861, 2021).
viral infection (continued). "During the early stage of viral infection, IFN-I expression is predominately driven by IRF3 and IRF7 after their activation through phosphorylation." (PMID 33690734, 2021). "In epithelial-like HEK293T and HeLa cells, NLRX1 acts as a negative regulator of RLR-mediated antiviral signaling, as it decreases type I IFN production following viral infection via interacting with the adaptor protein MAVS and inhibiting IRF3 dimerization." (PMID 33525671, 2021). "On the one side, we found ARID1A interacts with IRF3, a crucial transcription factor that regulates the production of IFN-I in response to virus infection." (PMID 34315861, 2021). "To further validate the inhibitory effect of FMDV VP3 on type-I IFN signaling, we examined IRF3 localization in FMDV VP3-overexpressing and control HEK293T cells following viral infection." (PMID 34578357, 2021). "We show here that during the early stage of viral infection, the acetylation of TBK1 was increased, and the acetylation of TBK1 at Lys241 enhanced the recruitment of IRF3 to TBK1." (PMID 32772249, 2021). "Upon virus infection, activated TBK1 phosphorylates IRF3 and triggers its nuclear translocation, which ultimately promotes the production of type I IFNs and ISGs." (PMID 34882534, 2021). "HSV-1 VP24 protein binds IRF3 to prevent TBK1/IRF3 interaction and block the phosphorylation and dimerization of IRF3 during viral infection." (PMID 33391252, 2020). "As a member of IRF transcription factor family that regulates IFN expression during viral infection, IRF1 plays a very important role in regulating the expression of IFNs and ISGs, in addition to NF-κB, IRF3, and IRF7." (PMID 32983049, 2020). "IRF3 is a transcription factor which induces the production of IFN-beta to amplify the IFN response, upon viral infection." (PMID 31956894, 2020). "MAVS also promotes activation of interferon regulatory factor 3 (IRF3) and NF-κB, leading to the production of type I interferon (IFN) and cytokines to against virus infection." (PMID 32349769, 2020). "Upon viral infection, cellular TBK1- and IKKi-mediated phosphorylation of serines 385 and 386 and the serine/threonine cluster between amino acids 396 and 405 of IRF3 lead to its conformational change and activation." (PMID 33391252, 2020). "TRIF has been shown to form a complex with TBK-1, a protein kinase that has been reported to directly phosphorylate IRF-3 and IRF-7 in response to viral infection or TLR3 and TLR4 stimulation based on in vitro kinase assays." (PMID 32373120, 2020). "In HEK293 cells, endogenous IRF3 is SUMOylated at K70 and K87 in its DBD, and viral infection slightly increases SUMOylation." (PMID 32645843, 2020). "During this process, IRF3 phosphorylation and nuclear translocation are essential for IFN-β production upon virus infection." (PMID 32117232, 2020). "Consistent with the cytokine levels, the knockdown of β-arrestin 2 significantly reduced the phosphorylation of TBK1, IRF3, IRF7, and STING and also the dimerization of IRF3 during virus infection." (PMID 33243993, 2020). "TRIM21 mediates the polyubiquitination and degradation of the DNA sensor DDX41 and the IRF transcription factors IRF3, IRF5, and IRF7 to negatively regulate the production of interferon-β during viral infection." (PMID 33061806, 2020). "A ligase within the PIAS family is responsible for the sumoylation of IRF3 and IRF7 observed after a viral infection, leading to the negative regulation of type I IFN gene expression, and PIAS1 is a mediator of IRF7 sumoylation." (PMID 33192313, 2020). "EcTBK1 was identified as a vital inhibitor in the viral infection processes of SGIV, by triggering the IRF3- and IRF7-regulated interferon promotor ISRE and IFN activity in our previous research." (PMID 32849631, 2020). "IRF-3, a key regulator of type I IFN gene expression, was also less activated upon viral infections in MTFMT-silenced cells." (PMID 32636430, 2020).
viral infection (continued). "In response to viral infection, among the IRF family members, particularly IRF-1, IRF-3, and IRF-7 are necessary for the production of type I IFN and also IFN-inducible genes (Bego, Mercier & Cohen, 2012)." (PMID 32566414, 2020). "The investigation on the mechanisms for the induction of IFNs showed that poly(dA:dT) treatment of the cells enhanced the phosphorylation of IRF3 and IRF7, the key and positive regulators of IFNs during viral infections." (PMID 33664729, 2020). "The IRF3-dependent pathway is primarily responsible for IFN and ISGs expression at the early stages of viral infection, while the ISGF3-dependent pathway is responsible at the later period of infection." (PMID 30984174, 2019). "We found markedly enhanced SeV-induced IRF3 phosphorylation and dimer formation in NLK−/− cells compared with those in wild-type cells after viral infection, indicating that NLK regulates SeV-induced IRF3 signaling." (PMID 31324787, 2019). "In the infected cells, TLR3 can recognize dsRNA and activate TBK1 by acting on the TRIF-dependent pathway; then, phosphorylated IRF3 is induced to translocate into nuclei; finally, it can induce the secretion of cytokines IFN-β against viral infection." (PMID 31975996, 2019). "In human fibroblast cell lines viral infection activated IRF7 and consequently upregulated MAP3K8, a kinase inhibiting IRF3 dimer formation and promoting the formation of IRF3-IRF7 heterodimers." (PMID 31178872, 2019). "Interferon regulatory factor 3 (IRF3) is a transcription factor that is constitutively expressed in AECs and plays an important role in mounting a rapid IFN response following viral infection." (PMID 31319869, 2019). "IRF3 plays, together with the closely related IRF7, an important role in the IFN-I signaling cascade and the control of viral infections." (PMID 30939763, 2019). "For example, both IRF3 and IRF7 are negatively regulated by SUMOylation following viral infection in order to turn off and limit responses." (PMID 30984161, 2019). "Following virus infection, IFN-β synthesis requires the phosphorylation and translocation of IRF-3 to the nucleus to initiate transcription of the IFN-β gene." (PMID 31083335, 2019). "The TBK1, a downstream transcription factor of IPS-1, mediates the activation of IRF3, leading to the induction of IFN-I following viral infections, and is also tightly regulated to effectively control viral infections and maintain immune homeostasis." (PMID 31330869, 2019). "The transcription of type I and type III IFN is also mediated by IFN regulatory factors (IRF3, IRF7), and toll like receptor 3 (TLR3) in response to virus infection." (PMID 31652893, 2019). "The phosphorylated TBK1 further activates IRF3 and induces the phosphorylated IRF3 to translocate into nuclei, and then it induced the secretion of cytokines IFN-β against viral infection." (PMID 31975996, 2019). "THOC7 interacted with MAVS, TBK1, IKKε, and IRF3 and, notably, the interaction was decreased with MAVS, but increased with TBK1 after virus infection, indicating that THOC7 have a significant function by targeting TBK1 in the antiviral response." (PMID 30769920, 2019). "During mammalian viral infections, interferon regulatory factor 7 (IRF7) partners with IRF3 to regulate the type I interferon response." (PMID 30356848, 2018). "Taken together, these studies highlight the importance of IRF3/5/7 phosphorylation and activation in the downstream of cytoplasmic/endosomal PRR signaling leading to type I IFN expression during virus infection." (PMID 30671058, 2018). "However, it was reported that in TRAF3-deficient MEFs RNA viruses can normally activate IRF3 and induce a modestly reduced level of IFNβ, suggesting that the function of TRAF3 can be substituted by other antiviral signaling for IFNs induction during viral infection." (PMID 29734366, 2018).
viral infection (continued). "Among nine IRFs, IRF1, IRF3, IRF5, and IRF7 play a pivotal role in the induction of IFN gene transcription during viral infection." (PMID 30671058, 2018). "Recent studies have revealed that STING acts as a scaffold protein for TBK-1 and IRF3 and links them to the MAVS complex in mitochondria upon viral infection." (PMID 29201911, 2017). "IFN-α, controlled primarily by IFN regulatory factor 3 (IRF-3) and IFN regulatory factor (IRF-7), plays a crucial role in host defense processes against viral infection." (PMID 28382020, 2017). "TLR9 activation in pDCs results in the phosphorylation and nuclear translocation of transcription factors IRF3 and IRF7, which induce IFNα/β expression in response to viral infection and DNA sensing." (PMID 28861085, 2017). "Indeed, HSV-1-induced activation of IRF3 and NF-κB and subsequent induction of downstream genes were enhanced in USP13 deficient mouse cells or in USP13-knockdown THP-1 cells, suggesting that the residual USP13-STING association restricts excessive activation of STING in response to viral infection." (PMID 28534493, 2017). "Following sensing of viral infection by RIG-I/MDA5 and activation of MAVS, TBK1 is activated which leads to the phosphorylation of the interferon regulatory factor 3 (IRF3)." (PMID 28883463, 2017). "In the resting state cells, IRF3 and IRF7 localize in cytoplasm, whereas poly(I:C) stimulation or virus infection induces their cytoplasmic-nuclear translocation." (PMID 28396670, 2017). "Following virus infection, engagement of the RLR or TLR3 pathway culminates in the phosphorylation of specific serine residues in the C-terminal part of IRF3 by TBK1 or IKKε." (PMID 29084253, 2017). "We reveal that HRS is important for activation of NF-κB, IκBα, and p38 during viral infections, suggesting that HRS plays critical roles in TLR7-mediated activation of NF-κB, p38 MAPK, and IRF3 pathways." (PMID 28854257, 2017). "The activation of TFs including NF-κB, AP1, IRF3 and IRF1, induced by viral infection, coordinately and cooperatively trigger IFNβ or IFNλ1 induction." (PMID 29020068, 2017). "The IFN-β promoter has been extensively studied, and a role for an enhanceosome consisting of IRF3, AP-1 (composed of ATF2 and c-jun), and NF-κB has been established in IFN-β expression in response to viral infection." (PMID 27795299, 2017). "It was shown that viral infection can induce TRIM26 expression, and that by modulating IRF3 and interferon-β this acts as a mechanism to evade the innate immune system." (PMID 27924031, 2017). "Mechanistically, viral infection induced TBK1-dependent ERRα stabilization, which in turn increased its binding to TBK1 and IRF3 to prevent the formation of a functional TBK1-IRF3 complex." (PMID 28591144, 2017). "Phosphorylation of the C-terminal serine (Ser) and threonine (Thr) residues is important for IRF3 and IRF7 activation following viral infection." (PMID 28396670, 2017). "It has been reported that phosphorylation of IRF3 at Ser386 induces dimerization and interaction with CBP and that phosphorylation at Ser396 occurs in response to viral infections." (PMID 26811330, 2016). "Upon viral infection, recognition of viral RNA by RIG-I induced a downstream signaling cascade, including MAVS, TBK1, IRF3." (PMID 27213432, 2016). "Coincident with enhanced IRF3 signalling and IFN-β production, Sdc4 mRNA and SDC4 protein were significantly increased in HEK293 cells and HepG2 cells on virus infection." (PMID 27279133, 2016). "We show that the TLR3 and RIG-I/MDA5 pathways participate in the regulation of SAMHD1 expression and find that IRF3 phosphorylation and nuclear translocation are critical aspects of SAMHD1 upregulation after IFN-α treatment and virus infection." (PMID 27411355, 2016). "The results suggest that SNRNP200 specifically regulates IRF3 activation upon RNA virus infection to promote IFNB1 induction and IFN effector responses, and thus demonstrates its importance in controlling viral infections." (PMID 27454487, 2016).
viral infection (continued). "After virus infection, IFN-β transcription requires IRF3, which is activated through phosphorylation, dimerization and nuclear translocation." (PMID 25763818, 2015). "The importance of IRF3 and IRF7 in regulating the early and late phases of IFN expression during viral infection was demonstrated through the generation of IRF3 and IRF7 knock-out mice." (PMID 25798928, 2015). "Although IRF3 activation and IFN-β production are essential for the host to prevent viral infection, aberrant or excessive IFN-β production can lead to the pathogenesis of human autoimmune diseases such as SLE." (PMID 25763818, 2015). "Synthetic dsRNA, PolyI:C, and dsRNA produced during viral infections induce interferon production and activate pro-apoptotic pathways involving PKR, RNase L, IRF3, Rig-I and JNK." (PMID 26263979, 2015). "During acute viral infections, including those by RSV, IRF3 is activated through serine/threonine phosphorylation, leading to its homo-dimerization and nuclear translocation." (PMID 26501312, 2015). "In mammals, once PRRs recognize a viral infection, a signaling cascade leads to the phosphorylation of IRF7 in the cytosol and to the translocation of IRF7 homodimer or IRF3/7 heterodimer into the nucleolus where they activate the type I IFN pathway." (PMID 26186542, 2015). "For example, during virus infection, Pin1 isomerized viral integrase as well as cellular IRF3 required for efficient virus replication and IRF-3-dependent production of IFN-β, respectively." (PMID 25874604, 2015). "By virus infection, activations of some certain PRRs such as TLR3, RIG-I and MDA5 result in the phosphorylation and nuclear translocation of IRF3 and IRF7." (PMID 25759845, 2015). "Interferon regulatory factor 3 (IRF3) is a transcription factor that mediates type-I interferon (IFN-I) expression, such as IFN-α and IFN-β, after viral infection." (PMID 26501312, 2015). "After viral infection, these key adaptors TRIF, MAVS and STING recruit the kinases TBK1 and IKKε to activate the transcription factor interferon-regulatory factor 3 (IRF3), leading to the production of type I inteferons and antiviral immune responses." (PMID 25763818, 2015). "At the same time, we demonstrated that virus infection increased TRIM26 expression and nuclear translocation, which promoted the ubiquitination and degradation of nuclear IRF3 leading to decreased IFN-β production and antiviral responses." (PMID 25763818, 2015). "Viral infection triggers host innate immune responses through activation of the transcription factors NF-κB and IFN regulatory factor (IRF)-3 leading to type I IFN production and anti-viral state in mammalian cells." (PMID 25538732, 2014). "Similar to IRF3, the transcription factor IRF7 is another key regulator of type I IFN induction and is critical for host defense against virus infections." (PMID 24743339, 2014). "After viral infection, IRF-3 is phosphorylated by IKKε and TBK1 and the phosphorylated IRF-3 then homodimerizes and translocates into the nucleus to activate type I IFN." (PMID 25538732, 2014). "Viral infection is sensed by endosomal Toll-like receptors (TLRs), which signal to activate NF-κB, IFN-regulatory factor 3 (IRF3), IRF7, and downstream transcription of cytokine and IFN-α/β genes." (PMID 25360880, 2014). "Virus infection results in the coordinate activation of NF-κB, ATF-2/c-Jun, IRF3, and IRF7 that assemble sequentially on this IFN-β enhancer region." (PMID 24722640, 2014). "Early during viral infection, engagement of PRRs leads to the transcription of type I IFN genes that are regulated by the transcription factor interferon regulatory factor 3 (IRF3), including IFN-β and limited species of IFN-α." (PMID 24904537, 2014). "To test this, we generated Irf3−/−×Irf5−/−×Irf7−/− TKO mice and defined their response to viral infection." (PMID 23300459, 2013).